GATA3 (GATA binding protein 3)
Diseases named in the same sentence as GATA3 in open-access papers (continued):
Sharing a sentence is not in itself a finding about the gene and the disease.
metastatic melanoma (2 papers, 2008 to 2015). A melanoma that has spread from its primary site to another anatomic site. "First immunization with DC vaccine of mice with metastatic melanoma resulted in the increase of the expression level of Tbet, GATA3 and RORg in comparison both with baseline and w/t group (compare C and B)." (PMID 26325576, 2015).
myocardial infarction (2 papers, 2024). Gross necrosis of the myocardium, as a result of interruption of the blood supply to the area, as in coronary thrombosis. "Studies in mGATA3KO mice have shown that the deficiency of GATA3-positive macrophages can improve cardiac function following myocardial infarction or pressure overload hypertrophy." (PMID 39822378, 2024). "Despite the lack of research focusing on the role of GATA3 in the pathogenesis and complications of cardiovascular diseases, a prior study has shed light on the significance of dampening GATA3 in improving cardiac function following myocardial infarction (MI) and pressure overload hypertrophy." (PMID 39768217, 2024). "GATA3 is not normally expressed in healthy cardiac tissues but usually accumulates in monocyte-derived macrophages in response to myocardial infarction (MI) and pressure overload hypertrophy." (PMID 39768217, 2024).
neuroendocrine carcinoma (2 papers, 2025). A malignant neuroendocrine neoplasm composed of cells containing secretory granules that stain positive for NSE and chromogranin. "This lack of expression of both markers in neuroendocrine carcinoma was also shown in other studies while some studies noted GATA3 expression." (PMID 39856762, 2025).
non-Hodgkin lymphoma (2 papers, 2022 to 2024). Distinct from Hodgkin lymphoma both morphologically and biologically, non-Hodgkin lymphoma (NHL) is characterized by the absence of Reed-Sternberg cells, can occur at any age, and usually presents as a localized or generalized lymphadenopathy associated with fever and weight loss. "TCR signaling activates a signaling axis that includes ITK, NF-κB, and GATA-3 and promotes chemotherapy resistance in non-Hodgkin lymphomas." (PMID 36457017, 2022).
olfactory neuroblastoma (2 papers, 2022 to 2024). An olfactory neuroblastoma arising in the paranasal sinus. "This is the first study reporting the immunohistochemical expression profile of SATB2, GATA3, and CDX2 in olfactory neuroblastoma (ONB)." (PMID 35522392, 2022).
ovarian tumor (2 papers, 2020 to 2025).
pancreatic ductal adenocarcinoma (2 papers, 2017 to 2021). An infiltrating adenocarcinoma that arises from the epithelial cells of the pancreas. "GATA3 positivity is associated with poor prognosis of pancreatic ductal adenocarcinoma." (PMID 34109184, 2021).
parasite (2 papers, 2013 to 2016). "Genes that encode full-length GATA3 and IL17RB were shown to be significantly increased in resistant sheep that had controlled parasite infection." (PMID 27973603, 2016). "To determine whether T-bet+GATA-3+ cells develop in unmanipulated immune reactions, we used different parasite infections that elicit Th2-biased immune responses." (PMID 23976880, 2013).
parathyroid disease (2 papers, 2020 to 2024). "Recently GATA-3 and parafibromin have been known to have a role in the pathogenesis of parathyroid diseases, and these markers have been attempted to be used in the diagnostic field of parathyroid tumors." (PMID 33114338, 2020).
Parkinson disease (2 papers, 2023 to 2024). A progressive degenerative disorder of the central nervous system characterized by loss of dopamine producing neurons in the substantia nigra and the presence of Lewy bodies in the substantia nigra and locus coeruleus. "The potential use of GATA3 as a novel biomarker for early detection of diseases like Parkinson’s disease and its role in predicting disease progression describes its importance in developing non-invasive diagnostic tools." (PMID 39768217, 2024). "In neurobiology, researchers are investigating GATA3’s importance for neuronal development and survival, with potential applications in neurodegenerative diseases such as Parkinson’s disease." (PMID 39768217, 2024).
periodontitis (2 papers, 2022 to 2023). An acute or chronic inflammatory process that affects the tissues that surround and support the teeth. "For the first time, effects of different genotypes were analyzed in periodontitis progression after periodontal therapy and during supportive treatment using systemic antibiotics demonstrating a slight association of GATA-3 gene locus with CAL." (PMID 35806269, 2022). "GATA-3 genotypes might be useful for predicting disease progression in severe periodontitis." (PMID 35806269, 2022). "In the present study, the influence of IL-1, IL-4, GATA-3 and COX-2 polymorphisms on the outcomes of non-surgical therapy with and without antibiotics and 2 years of maintenance was analyzed in Caucasian periodontitis patients." (PMID 35806269, 2022). "The aim of the present exploratory subanalysis was to evaluate the role of the IL-1A −889, IL-1B +3954, IL-4 −34, IL-4 −590, GATA-3 IVS4 +1468 and COX-2 −1195 gene loci in patients with periodontitis after a non-surgical periodontal therapy with or without additional adjunctive systemic antibiotics." (PMID 35806269, 2022).
pneumonia (2 papers, 2020 to 2021). An acute, acute and chronic, or chronic inflammation focally or diffusely affecting the lung parenchyma, caused by an infection in one or both of the lungs (by bacteria, viruses, fungi, or mycoplasma.). "The expression levels of CD66, CD40L and GATA3 were increased in patients with pneumonia, whereas reversed after being co‐cultured with TCs." (PMID 34841705, 2021). "For selected patients (n=3 in control; n=3 in ICI-pneumonia; n=2 in ICI-pneumonitis), along with chemokine/cytokine receptors, we also investigated expression of key transcription factors including T-bet (Th1), GATA3 (Th2), RoRγT (Th17), and FoxP3 (Treg)." (PMID 33552049, 2020).
salivary gland carcinoma (2 papers, 2018 to 2025). A carcinoma that arises from the major or minor salivary glands. "Negative stains include GATA3, adipophilin, HER2/neu (w/occasional membrane positivity), CK20, and GCDFP-15, all of which may indicate the alternative diagnosis of a mammary, prostate, or salivary gland carcinoma." (PMID 41551756, 2025).
sarcomatoid mesothelioma (2 papers, 2020). A diffuse malignant mesothelioma arising from the pleura and less often the peritoneum. "Since sarcomatoid histotype often does not express these markers and most commonly only stains for pan-Cytokeratin, GATA binding protein 3 (GATA-3) has been proposed as sensitive and specific biomarker for distinguishing sarcomatoid mesothelioma from sarcomatoid carcinoma of the lung." (PMID 36046389, 2020). "BAP-1 negativity and GATA binding protein 3 (GATA3) positivity have been recently described to be very helpful in ruling out PSC and supporting the diagnosis of sarcomatoid mesothelioma." (PMID 32149365, 2020).
Sézary syndrome (2 papers, 2022 to 2025). "In the case of Sézary syndrome, it was found that dysfunction of proteasome in T cell led to the accumulation of cytotoxic T-lymphocyte antigen-4 (CTLA-4) and GATA binding protein 3 (GATA3)." (PMID 41281743, 2025).
skin adnexal tumors (2 papers, 2017 to 2025). "Like GATA3, TRPS1 is expressed in cutaneous and skin adnexal tumors." (PMID 40025593, 2025).
spindle cell neoplasm (2 papers, 2024 to 2025). A benign or malignant neoplasm characterized by the presence of neoplastic spindle cells. "A liver biopsy showed a malignant pleomorphic spindle cell neoplasm with diffuse strong staining for GATA3, weak PAX8 expression and negativity for multiple cytokeratins." (PMID 40691018, 2025). "We present a case of a GATA3+ malignant spindle cell neoplasm diagnosed on a liver biopsy that was determined to be metastatic sarcomatoid ChRCC at autopsy." (PMID 40691018, 2025). "In the setting of a kidney mass with a biopsy at a metastatic site showing a GATA3 positive spindle cell neoplasm, the differential diagnosis should include sarcomatoid ChRCC." (PMID 40691018, 2025).
tuberculosis (2 papers, 2011 to 2012). A chronic, recurrent infection caused by the bacterium Mycobacterium tuberculosis. "Interestingly, in-vitro purified protein derivative (PPD)-stimulated peripheral blood mononuclear cells, obtained from active tuberculosis patients, have reduced GATA-3 mRNA levels." (PMID 21829471, 2011). "As a group healthy volunteers had lower transcript levels for all the three target genes investigated compared to tuberculosis patients, (IL-4, p = 0.03; IFN-α, p = 0.009 and GATA-3, p = 0.04)." (PMID 22509293, 2012).
type 2 diabetes (2 papers, 2018 to 2024). "Our findings demonstrate that genetic variation of the transcription factor GATA3, not STAT4, is associated with the risk of type 2 diabetes in the Bangladeshi population." (PMID 30044774, 2018). "Thus, the present study postulates that the genetic variation of the transcription factor GATA3, not STAT4, is associated with the risk of type 2 diabetes in the Bangladeshi population." (PMID 30044774, 2018).
urachal adenocarcinomas (2 papers, 2018 to 2022). "The example of GATA3 in particular illustrates the need of rigorous case selection of primary bladder and/or urachal adenocarcinomas in the studies." (PMID 29721106, 2018). "Useful biomarkers of urachal adenocarcinomas, like alpha-methylacyl-CoA racemase (AMACR, p504s), CD15 (Leu-M1), carcinoembryonic antigen (CEA), CK34βE12 (high-molecular weight cytokeratin), GATA binding protein 3 (GATA3), mucin 2 (MUC2), and mucin 5AC (MUC5AC), should be taken into consideration." (PMID 36010242, 2022).
uterine carcinoma (2 papers, 2016 to 2021). A carcinoma involving a uterus. "Use of a panel of markers such as GATA3 and CD10 and awareness of the lack of specificity of PAX2 will help avoid misdiagnosis, particularly when MLA and other uterine carcinomas showing mesonephric-like differentiation are suspected." (PMID 33919505, 2021).
vascular neoplasm (2 papers, 2024 to 2025). A benign, intermediate, or malignant neoplasm arising from vascular tissue including arteries, veins, venous sinuses, lymphatic vessels, arterioles and capillaries. "In our case, immunoreactivity for GATA3, estrogen, and progesterone receptors confirmed the breast tissue origin, while negative PAX8 and ERG stains ruled out Müllerian origin and vascular neoplasms, respectively." (PMID 41393763, 2025). "Immunohistochemical staining was negative for GATA-binding protein 3 (GATA-3), pan-keratin, and epithelial membrane antigen (EMA), and positive for CD34 and CD31, supporting the diagnosis of a benign vascular tumor." (PMID 39669857, 2024).
acute coronary syndrome (1 paper, 2022). Signs and symptoms related to acute ischemia of the myocardium secondary to coronary artery disease. "A recent study found a significantly increased TBET/GATA3 mRNA ratio in patients with AMI throughout most of the first 20 h after symptom onset, which suggested that TBX21 could promote the progression of acute coronary syndrome." (PMID 35498008, 2022).
airway allergy (1 paper, 2022). "We believe that the complex formations of livin/GATA3 enhances the stability of livin expression that triggers the high expression of IL-4 by activating the transcription of IL4 gene and facilitates CD4+ T cells to differentiate into Th2 cells, and causes airway allergy." (PMID 35717553, 2022). "It is reported that the expression level of GATA3 in CD4+ T cells of AAD mice was significantly increased compared with that of naïve mice, which suggests that GATA3 is involved in the development of airway allergy." (PMID 35717553, 2022).
alopecia (1 paper, 2013). Hair loss usually from the scalp. "Since the mouse juvenile alopecia phenotype (patchy hair loss) is distinct from that of these conditionally-targeted mutants (complete baldness)—whatever its molecular basis—we believe that Gata3jal likely offers a novel mutant allele, compared to the existing set of engineered Gata3 disruptions." (PMID 23659281, 2013). "In addition, we describe complementation testing between jal and engineered null alleles of two co-localizing candidate genes, one of which (Gata3, for GATA binding protein 3) we identify as the likely basis of the juvenile alopecia phenotype in mice." (PMID 23659281, 2013).
Alzheimer disease (1 paper, 2024). A progressive, neurodegenerative disease characterized by loss of function and death of nerve cells in several areas of the brain leading to loss of cognitive function such as memory and language. "In neurodegenerative disorders like Alzheimer’s disease, GATA3’s role in neuronal function and maintenance suggests that its dysregulation may accelerate disease progression." (PMID 39768217, 2024).
anaphylaxis (1 paper, 2021). An acute hypersensitivity reaction that occurs from exposure to an allergen. "Conversely, allergens induce GATA3+Tfh13 cells driving high-affinity IgE production and anaphylaxis." (PMID 34066544, 2021). "Moreover, inhibition of IL-13 or GATA3 may be therapeutic targets for anaphylaxis." (PMID 34066544, 2021).
anaplastic large cell lymphoma (1 paper, 2018). Anaplastic large cell lymphoma (ALCL) is a rare and aggressive peripheral T-cell non-Hodgkin lymphoma, belonging to the group of CD30-positive lymphoproliferative disorders, which affects lymph nodes and extranodal sites. "And in anaplastic large cell lymphoma, the absence of the GATA3 protein in addition to the presence of suppressive histone (H3K27) trimethylation at the GATA3 promoter suggests epigenetic regulation of GATA3 as a mechanism involved in disease pathogenesis." (PMID 30463912, 2018).
aneurysm (1 paper, 2021). Bulging or ballooning in an area of an artery secondary to arterial wall weakening. "However, AngII-treated Apoe−/−Light−/− mice aneurysms showed reduced expression of the Th2 transcription factor Gata3 gene, and augmented mRNA levels of the Th17 transcription factor Rorc gene." (PMID 34829747, 2021).
aortic aneurysm (1 paper, 2013). A ruptured aneurysm located in the wall of the proximal portion of the descending aorta proceeding from the arch of the aorta. "Ang II infusion significantly decreased the T-bet mRNA level but increased GATA-3 expression in the aortic aneurysms compared to saline-treated controls, and these effects were markedly reversed in Ang II/DBZ-treated group." (PMID 24358274, 2013). "The ratio of T-bet/GATA-3 was also significantly lower in Ang II/DBZ-treated aortic aneurysms compared to Ang II-treated group." (PMID 24358274, 2013).
aplastic anemia (1 paper, 2014). Anemia resulting from bone marrow failure (aplastic or hypoplastic bone marrow). "A previous study demonstrated that decreased T-bet expression and increased GATA-3 expression occurred in PBMCs of patients with different solid tumors, whereas increased T-bet expression and decreased GATA-3 expression were found in aplastic anemia patients." (PMID 25705124, 2014).
atopic asthma (1 paper, 2014). An asthma that is characterized by symptoms that are triggered by an allergic reaction caused by inhaled allergens such as dust mite allergen, pet dander, pollen and mold. "In a mouse model of atopic asthma, pharmacologic activation of PPARG reduces the canonical Th2 cytokines IL4 and IL13 and GATA3 protein in lung extracts." (PMID 24426833, 2014).
autism spectrum disorder (1 paper, 2023). A spectrum of developmental disorders that includes autism, and Asperger syndrome. "The higher level of Gata3 in the hypothalamus of pigs exposed to MIA and postnatal stress agrees with the higher abundance of the protein GATA3 in the brain of a mouse line that models autism spectrum disorder phenotypes." (PMID 37851674, 2023).
Autoimmune Addison's Disease (1 paper, 2014). "GATA3 has been implicated in the homeostasis and regulation of CD8+ T-lymphocytes and could therefore contribute to primary T-lymphocyte dysregulation in autoimmune Addison's disease." (PMID 24614117, 2014).
autoimmune pancreatitis (1 paper, 2022). "In IgG4-related Sclerosing Cholangitis and type 1 Autoimmune Pancreatitis (IgG4-SC/AIP) and Chronic Periaortitis (CP) patients, a dominant infiltration of GATA3+ Th2 cells were observed in the affected tissues." (PMID 35432312, 2022).
autoimmune uveitis (1 paper, 2017). An autoimmune form of uveitis (disease). "In a recent study in another autoimmune uveitis entity named Vogt-Koyanagi-Harada (VKH) disease, we also found a hypermethylation of the GATA3, IL-4 and TGF-β promoters with a small difference." (PMID 28969068, 2017).
babesiosis (1 paper, 2023). Babesiosis refers to a condition caused by microscopic parasites that infect the red blood cells. "In dogs with mild/moderate babesiosis the expression of GATA3 was highest, while in dogs with advanced babesiosis the highest expression of INF-γ and SOCS3 was recorded." (PMID 36739305, 2023).
Bartonella infection (1 paper, 2017). "Higher expression levels of IL-10 and IFN-γ were associated with current infections with Babesia and Bartonella, and cowpox virus, respectively, while lower expression levels of Gata3 were associated with cowpox virus infection and marginally associated with Babesia and Bartonella infection." (PMID 28817724, 2017).
Benign Ovarian Brenner Tumor (1 paper, 2021). A benign transitional cell tumor that arises from the ovary and is composed of a fibrotic stroma and nests of transitional cells without evidence of atypia. "GATA3 is considered a transcriptional activator for the regulation of T-cell development and several inflammatory and allergic responses and was suggested as a regulator in benign ovarian Brenner tumors and serous tumors with prognostic value." (PMID 33921111, 2021).
Bovine mastitis (1 paper, 2023). INFLAMMATION of the UDDER in cows. "For instance, the differential expression of genes (CX3CR1, RHOH, LPAR5, and GATA3) overlapped with dMHB discriminant signatures related to SC subclinical mastitis have been found relevant to immune responses to bovine mastitis." (PMID 37373515, 2023).
breast fibroadenoma (1 paper, 2025). "Complete surgical excision was performed, and histopathological evaluation—including immunohistochemistry for estrogen receptor, progesterone receptor, GATA3, and p63—confirmed ectopic breast fibroadenoma." (PMID 41040519, 2025).
breast NETs (1 paper, 2022). "The transcription factor GATA binding protein 3 (GATA3), responsible for mammary gland development and for luminal transcription programme, was the most frequently mutated gene in breast NETs." (PMID 36085291, 2022). "For example, MEN1 was mutated in only 6% of breast NETs and 37% in PNETs (adjusted p value 0.00050), and GATA3 pathogenetic or unknown variants were only found in 17.0% of breast NETs and 0% in PNETs (adjusted p value 0.0010)." (PMID 36085291, 2022). "In agreement with this, the Reis-Filho group reported GATA3 pathogenetic or unknown variants in one of their 10 breast NET samples." (PMID 36085291, 2022).